MTOR (mechanistic target of rapamycin kinase)
Diseases named in the same sentence as MTOR in open-access papers (continued):
Sharing a sentence is not in itself a finding about the gene and the disease.
Kawasaki disease (3 papers, 2024 to 2025). A rare inflammatory disease characterized by an acute febrile, systemic, self-limiting, medium-vessel vasculitis primarily affecting children. "Here, we show that the mTOR signalling cascade is activated by luminal myofibroblasts that emerge in patients with Kawasaki disease, Takayasu’s arteritis and giant cell arteritis." (PMID 39271773, 2024). "Through the AMPK/mTOR axis, FA exhibits tissue-specific regulation: in Kawasaki disease, it activates AMPK/mTOR to inhibit NF-κB-mediated inflammation and apoptosis, while in microglia, it downregulates NLRP3 inflammasome expression to alleviate neuroinflammation." (PMID 40573306, 2025).
lactic acidosis (3 papers, 2010 to 2024). Metabolic acidosis characterized by the accumulation of lactate in the body. "Paradoxically, while lactate can support cell growth and metabolism, lactic acidosis in the microenvironment uncouples mTOR activation and suppresses proliferation particularly in immune cells." (PMID 38968363, 2024). "The lactic acidosis-induced cell cycle arrest may be caused by many changes, including the induction of AMPK, mTOR inhibition, TXNIP and cell cycle arrest caused by the induction p57, p21 and other inhibitors of cellular proliferation." (PMID 20844768, 2010). "Taken together, these data supported the notion that lactic acidosis triggers a cellular starvation response similar to that of glucose starvation, with AMPK activation and mTOR inhibition." (PMID 20844768, 2010). "There are many possible explanations as to how lactic acidosis leads to AMPK activation, mTOR inhibition and other features of the starvation response." (PMID 20844768, 2010).
lactotroph adenomas (3 papers, 2018 to 2023). "In addition, they demonstrated that the mTOR activation caused lactotroph adenoma in the mice by activating the pituitary tumor transforming gene 1 (PTTG1)." (PMID 37109772, 2023). "Adding to these data, cabergoline, a first-line treatment for lactotroph adenomas, was recently shown to suppress the prolactin hypersecretion and reduce the tumor size via the mTOR inhibition pathway in a rat pituitary tumor." (PMID 37109772, 2023). "Other therapeutic options have been proposed for DA resistant prolactinomas, such as metformin, selective estrogen modulators, somatostatin analogues, tyrosine kinase inhibitors, inhibitors of mammalian target of rapamycin (mTOR), immune checkpoint inhibitors and peptide radio-receptor therapy." (PMID 36928728, 2023).
laryngeal tumor (3 papers, 2016 to 2022). "Since ferroptosis can be negatively regulated by SLC3A2/mTOR axis, our results suggest that targeting SLC3A2 may be an underlying approach for laryngeal tumor therapy." (PMID 35057861, 2022). "Notably, the model predicts that lncRNA GAS5, which scored second, inhibits proliferation and metastasis of laryngeal neoplasms by regulating the PI3K/AKT/mTOR signaling pathway, according to a recent study in 2020." (PMID 35058974, 2021). "However, it will be of interest to correlate the levels of pH2AH with those of mTOR activation in laryngeal tumors to provide a more accurate hypothesis of the pH2AH inducers." (PMID 27166270, 2016).
learning disability (3 papers, 2021 to 2023). A group of disorders that affect a person's ability to learn or process specific types of information which is in contrast to his/her apparent level of intellect. "Indeed, mTOR dysregulation has been implicated in various brain disorders including ASD and learning disability, and therefore, the regulation of mTOR activation to an appropriate level is important for neurogenesis in brain development." (PMID 36005637, 2022).
Legionella infection (3 papers, 2016 to 2024). "Addition of the MTOR inhibitors PP242 or rapamycin to synchronized Legionella infections of Myd88-/- BMMs reduced phosphorylation of S6K1 and its substrate rS6p." (PMID 27942021, 2016). "Blocking MTOR function in Legionella infections through various approaches destabilized the Legionella-containing vacuole (LCV), led to its premature rupture and the release of bacterial products into the host cytosol, which in turn activated a host cell death response." (PMID 28357391, 2017). "Legionella infections could be an excellent model system to decipher how MTOR controls SREBP1/2 and lipogenesis - a key cellular process that is still poorly understood in primary macrophages." (PMID 28357391, 2017). "Thus, the role of the TLR adaptor Myd88, which is required for LPS-induced MTOR signaling, was investigated in the context of Legionella infection." (PMID 27942021, 2016). "In this aspect, Legionella infection could be an invaluable model to elucidate the mechanism of MTOR-induced lipogenesis." (PMID 27942021, 2016).
limb ischemia (3 papers, 2022 to 2024). A ischemia that involves the limb. "THP was recently reported to modulate the PI3K/Akt/mTOR pathway to protect against limb ischemia/reperfusion injury." (PMID 35935870, 2022). "In a limb ischemia model, miR-486b-5p was previously shown to target PTEN, activating the AKT/MTOR/HIF-1α pathway and increasing angiogenesis." (PMID 39120274, 2024).
Listeria infection (3 papers, 2018 to 2022). "Specifically, myelopoiesis requires mTOR signaling and loss of mTOR dampens innate immune responses against Listeria monocytogenes infection." (PMID 30619850, 2018). "We were struck by the modification of four key regulators of autophagy by ISGylation, in particular the modification of mTOR and WIPI2 following infection in wild-type animals following Listeria infection and modification of AMBRA1 and RAB7 following infection in USP18C61A/C61A animals." (PMID 31772204, 2019).
liver cysts (3 papers, 2011 to 2018). "Studies outlined the role of mammalian target of rapamycin (mTOR) in the pathogenesis of renal and hepatic cyst formation." (PMID 23304619, 2012). "Sirolimus, an mTOR inhibitors, was started because of preliminary data suggesting a potential benefit of mammalian target of rapamycin (mTOR) inhibitor therapy on hepatic cysts growth." (PMID 23304619, 2012). "Because of preliminary data suggesting a potential benefit of mammalian target of rapamycin (mTOR) inhibitors therapy on hepatic cyst growth, CsA was stopped and sirolimus started at 0.5 mg/d to achieve serum levels between 4 and 6 ug/L." (PMID 23304619, 2012). "Studies outlined the role of the mammalian target of rapamycin (mTOR) in the pathogenesis of renal and hepatic cyst formation and growing, and experimental studies suggest mTOR inhibitors efficacy as treatment in ADPKD." (PMID 23304619, 2012). "The mTOR inhibitor effect on hepatic cysts growth still needs to be determined." (PMID 23304619, 2012). "Randomized studies are needed to determine the efficacy of mTOR inhibitors on hepatic cyst growing." (PMID 23304619, 2012). "However, no randomized study has been performed yet to evaluate the effect of mTOR inhibitors in reducing hepatic cyst growth in ADPKD patients." (PMID 23304619, 2012). "mTOR inhibitors such as everolimus inhibit cell proliferation and might thereby reduce growth of liver cysts." (PMID 22104015, 2011). "Recent studies have shown that somatostatin and mTOR inhibitors may have benefit hepatic cyst." (PMID 23304619, 2012). "The mTOR inhibition effect on hepatic cyst progression is unknown." (PMID 23304619, 2012). "A slowing effect of mTOR inhibitors (or absence of slowing effect of mTOR inhibitors) on hepatic cysts growth still needs to be determined." (PMID 23304619, 2012). "Hepatic cysts epithelia express a high level of mTOR suggesting that mTOR inhibitors may have an effect in downregulating hepatic cyst growth, but no randomized study has been performed yet to evaluate the effect of this therapy." (PMID 23304619, 2012).
low grade glioma (3 papers, 2020 to 2022). A grade I or grade II glioma arising from the central nervous system. "Laplante and Sabatini found that the mammalian target of rapamycin (mTOR) signaling pathway is responsible for carboplatin resistance in pediatric low-grade glioma." (PMID 34065991, 2021).
lupus erythematosus (3 papers, 2012 to 2023). An autoimmune, connective tissue chronic inflammatory disorder affecting the skin, joints, kidneys, lungs, heart, and the peripheral blood cells. "It would seem that, similar to lupus erythematosus, the mTOR pathway is responsible for Treg depletion, and consequently inhibition of this pathway could have benefits in the therapeutic management of patients." (PMID 36902341, 2023). "Moreover, the induction of necrosis in CD4−/8− T cells of Lupus erythematosus patients was reported to be mTOR dependent." (PMID 33924101, 2021).
lymphatic disease (3 papers, 2012 to 2020). "Sirolimus and everolimus are mTOR inhibitors that act downstream of most lymphatic disease driving mutations in the PI3K/AKT/mTOR pathway and have been proven to be remarkably effective at stabilizing or reversing disease manifestations in some patients with LAM, GLA, CCLA, and KLA." (PMID 32945117, 2020). "Furthermore, studies demonstrated the efficacy of the mammalian target of rapamycin (mTOR) inhibitor sirolimus for these lymphatic diseases." (PMID 31236308, 2019).
macrodactyly (3 papers, 2020 to 2022). "However, now it is clear that postzygotic somatic mutations in the PIK3CA/AKT/mTOR pathway may be a cause of macrodactyly." (PMID 34869816, 2022). "In this study, we demonstrated that PIK3CA was mutated in BMSCs derived from overgrown bones in macrodactyly patients and the activating mutations resulted in hyperactivation of PI3K/AKT/mTOR signaling pathway and enhanced osteogenic differentiation." (PMID 32632138, 2020). "Although PI3K/AKT/mTOR cell-signaling pathway has been shown to play an important role in macrodactyly, whether or not this pathway contributes to bone malformation in macrodactyly was unknown." (PMID 32632138, 2020).
malignant fibrous histiocytoma (3 papers, 2014 to 2023). "In the present study, we demonstrate that an mTOR inhibitor, rapamycin, induces autophagy in the Nara-H malignant fibrous histiocytoma (MFH) cell line through the activation of ERK1/2." (PMID 24676456, 2014).
MALT lymphoma (3 papers, 2019 to 2024). An indolent, extranodal type of non-Hodgkin lymphoma composed of small B-lymphocytes (centrocyte-like cells). "We found that the prognosis was poorer and more prone to relapse and metastasis in the MTOR mutant group, and mutations in this gene can work as a biomarker of a poor prognosis in the alimentary tract MALT lymphoma." (PMID 39054516, 2024).
melasma (3 papers, 2021 to 2025). "Taken together, 590 nm LED inhibited HMEC-1 migration, tube formation and the secretion of VEGF and SCF, predominantly through the inhibition of the AKT/PI3K/mTOR pathway, which may serve as a novel therapeutic option for melasma." (PMID 36552713, 2022). "Furthermore, the investigation into 590 nm LED irradiation, which inhibits angiogenesis and the secretion of pro-melanogenic factors by endothelial cells via the AKT/PI3K/mTOR pathway, represents a novel therapeutic option that directly addresses the vascular component of melasma." (PMID 41154805, 2025). "Similarly, the 1064 nm laser, which is effective for melasma treatment, can downregulate the PI3K/AKT/mTOR pathway, enhance melanocyte autophagy, and accelerate melanin metabolism." (PMID 41154805, 2025).
Mitochondrial myopathy (3 papers, 2023 to 2024). "In mitochondrial myopathy, its target is the mTORC1 protein, which is a part of the “mammalian target of rapamycin” (mTOR) complex and is linked to cellular homeostasis." (PMID 39323625, 2024). "Recent studies have shown that mTOR signaling controls mitochondrial dynamics, and thereby participates in the progression of mitochondrial myopathy and cancer." (PMID 37569500, 2023).
mucolipidosis IV (3 papers, 2016 to 2021). "Mucolipidosis, Type IV (MLIV) is caused by mutations in MCOLN1 (Mucolipin 1), an endo-lysosomal pH sensitive channel that facilitates diffusion of monovalent and divalent ions and facilitates lysosomal and autophagic regulation via its interaction with TFEB and mTOR signaling." (PMID 32351971, 2020).
mucosal melanoma (3 papers, 2019 to 2025). A melanoma that arises from a mucosal site. "Mucosal melanoma (MM) is a poorly responsive, rare and aggressive subtype with paucity of targetable recurrent driver mutations, although Ras/MAPK and PI3K/AKT/mTOR signaling pathway activations are common." (PMID 40568110, 2025). "Activation of one or both the Ras/MAPK and PI3K/Akt/mTOR signal transduction pathways are known to mediate oncogenicity of several canine and human cancers, including mucosal melanomas." (PMID 36590793, 2022).
myxofibrosarcoma (3 papers, 2020 to 2024). A malignant fibroblastic neoplasm arising from the soft tissue. "An inhibitor of RAC and mTOR exerts an antitumor effect, revealing a potential treatment strategy for high-risk myxofibrosarcoma patients." (PMID 33335550, 2020).
nephrotic syndrome (3 papers, 2014 to 2025). A collection of symptoms that include severe edema, proteinuria, and hypoalbuminemia; it is indicative of renal dysfunction. "The data suggested that mTOR inhibition suppressed the expression of nephrotic-syndrome-related chemokines in the THP-1 cells and human primary monocytes." (PMID 25257976, 2014).
neurocutaneous disorders (3 papers, 2017 to 2025). "The shared genetic hallmark of neurocutaneous syndromes lies in somatic mutations disrupting core developmental pathways—including mTOR, Ras-MAPK, and Gαq-PLCβ signaling—leading to pluripotent progenitor cell dysregulation, tissue malformations, and tumorigenesis." (PMID 40979205, 2025). "mTOR’s central action on cell growth regulation occurs in other neurocutaneous disorders as well for NF1 and SWS." (PMID 28367137, 2017). "For instance, the mechanistic target of rapamycin (mTOR) signaling cascade plays a central role in seizures and epileptogenesis in numerous acquired and genetic disorders, including several neurocutaneous disorders." (PMID 28367137, 2017).
obstructive sleep apnea (3 papers, 2022 to 2023). "Other targeted pathways reported for the effects of A. graveolens in neurological disorders include Nrf2 and NF-κB pathways; BDNF/ERK/mTOR (antidepressant); CNTF/CNTFRa/JAK2/STAT3 (cerebral blood flow decreases); and SIRT1/PGC-1a (obstructive sleep apnea)." (PMID 37570794, 2023).
oral cavity cancer (3 papers, 2015 to 2025). A primary or metastatic malignant neoplasm involving the oral cavity. "In summary, this study demonstrates the utility of the mTOR inhibitor rapamycin and the MEK1/2 inhibitor PD901 in syngeneic models of oral cavity cancer." (PMID 26506415, 2015). "Here, we characterized the anti-tumor and immune effects of rapamycin, an FDA-approved inhibitor of mTOR signaling, and an investigational MEK1/2 inhibitor PD0325901 in these syngeneic MOC1 and 2 murine models of Ras-mutant oral cavity cancer." (PMID 26506415, 2015).
oropharyngeal cancer (3 papers, 2014 to 2025). Carcinoma, predominantly squamous cell, arising from the epithelial cells of the oropharynx. "The second was to elucidate mTOR complex expression in 80 oropharyngeal cancer tissues and to examine the relationship between mTOR complex expression and survival in patients with OPSCC." (PMID 33482765, 2021).
ovarian diseases (3 papers, 2016 to 2023). "SIRTs and SIRTs-related signaling molecules and drugs regulating mTOR can be used for characterization, prediction, and regulation of ovarian functions, as well as for diagnostics and treatment of ovarian disorders." (PMID 27886120, 2016). "However, the mechanism of PLB in PCOS and the interaction with the PI3K/Akt/mTOR signaling pathway in the pathogenesis of ovarian diseases remain unclear." (PMID 33029296, 2020).
ovarian endometriosis (3 papers, 2022 to 2023). A non-neoplastic disorder characterized by the growth of endometrial tissue in the ovaries. "Prior studies have suggested that EPHA3 plays a role in treating ovarian endometriosis, potentially promoting apoptosis and autophagy of macrophages via the inhibition of the mTOR signaling pathway and reducing oxidative stress." (PMID 37340323, 2023).
Pancreatic neuroendocrine carcinomas (3 papers, 2015 to 2025). "Pancreatic neuroendocrine carcinomas are known to be responsive to mTOR inhibition, suggesting that MTOR inhibition might have been a viable clinical strategy." (PMID 29599906, 2018).
pilocytic astrocytoma (3 papers, 2014 to 2024). Pilocytic astrocytoma is a rare subtype of low-grade glioma of the central nervous system characterized by a well circumscribed, often cystic, brain tumor with a discrete mural nodule and long, hair-like projections that extend from the neoplastic astrocytes. "Specifically, genomic profiling based on clinical-grade NGS could identify whether PTEN loss or other GAs activating the mTOR pathway are present alongside the BRAF fusion in a pilocytic astrocytoma of patient, thus suggesting a potential responsiveness to combined sorafenib/mTOR targeted therapy." (PMID 24422672, 2014). "Interestingly, in murine models of pilocytic astrocytoma, the KIAA1549-BRAF fusion hyperactivates the mTOR pathway, as does loss of PTEN." (PMID 24422672, 2014).
polyposis (3 papers, 2014 to 2023). "In summary, our data support a key role of deregulated translation in Myc-driven polyposis and exploitable synthetical lethality of mTOR inhibition and Myc." (PMID 37138032, 2023). "Endoscopic images from previously unpublished cases in the mTOR inhibitor group demonstrate severe polyposis throughout the GI tract." (PMID 33822054, 2021). "In comparison, we observed overall modest levels and more focal staining for phospho-S6 and phospho-mTOR in colon tissues of control mice or in colon tissues of CDX2P-CreERT2 Apcfl/fl mice with TAM-induced polyposis that had been treated with RAP." (PMID 24763434, 2014).